SFXN3 (sideroflexin 3)
Description:
Mitochondrial serine transporter that mediates transport of serine into mitochondria, an important step of the one-carbon metabolism pathway. Mitochondrial serine is converted to glycine and formate, which then exits to the cytosol where it is used to generate the charged folates that serve as one-carbon donors.
Synonyms: SFX3; SLC56A3; BA108L7.2
Tractability: Antibody: UniProt predicts a signal peptide or a membrane-spanning region. PROTAC: ubiquitination databases record sites on it; its protein half-life has been measured.
Gene: Protein-coding gene on chromosome 10 (101,031,229 to 101,041,244, forward strand). Ensembl gene ENSG00000107819.
Subcellular location: Mitochondrion membrane
Subcellular location (Human Protein Atlas): Mitochondria
Gene Ontology:
Molecular function: L-serine transmembrane transporter activity; protein binding; transmembrane transporter activity; monoatomic ion transmembrane transporter activity
Biological process: mitochondrial transmembrane transport; one-carbon metabolic process; serine import into mitochondrion; L-serine transport; monoatomic ion transmembrane transport; monoatomic ion transport; transmembrane transport
Cellular component: mitochondrial membrane; mitochondrion; mitochondrial inner membrane; membrane
Genetic constraint (gnomAD): Loss-of-function variants: 31 observed, 40.8 expected, observed/expected ratio (o/e) 0.76, 90% interval 0.57 to 1.03. The upper end of that interval is the gene's LOEUF score, 1.03, which puts it in group 4 of 6, group 1 being the genes least tolerant of losing a copy. Missense variants: 366 observed, 427.24 expected, observed/expected ratio (o/e) 0.86, 90% interval 0.79 to 0.93. Synonymous variants: 157 observed, 167.88 expected, observed/expected ratio (o/e) 0.94, 90% interval 0.82 to 1.07.
Homologues: Orthologues: chimpanzee SFXN3 (99% identical), macaque SFXN3 (98% identical), pig SFXN3 (95% identical), dog SFXN3 (95% identical), guinea pig SFXN3 (94% identical), mouse Sfxn3 (94% identical), rat Sfxn3 (88% identical), rabbit SFXN3 (87% identical), tropical clawed frog sfxn3 (77% identical), zebrafish sfxn3 (76% identical), Caenorhabditis elegans sfxn-1.5 (54% identical), Drosophila melanogaster Sfxn1-3 (54% identical), and 4 more. Paralogues in human: SFXN1 (76% identical), SFXN2 (55% identical), SFXN5 (40% identical), SFXN4 (21% identical).
Diseases named in the same sentence as SFXN3 in open-access papers:
SFXN3 is named in the same sentence as 16 diseases in open-access papers, as found by Europe PMC text mining. Sharing a sentence is not in itself a finding about the gene and the disease. The quoted sentences say what the papers report.
acute myeloid leukemia (3 papers, 2022 to 2024). Acute myeloid leukemia (AML) is a group of neoplasms arising from precursor cells committed to the myeloid cell-line differentiation. "SFXN3 expression levels in CHOL, HNSC, KIRC, acute myeloid leukemia (LAML), PAAD, PCPG, and sarcoma (SARC) were upregulated compared with those in the corresponding normal controls in the GEPIA database (all p < 0.05)." (PMID 36159813, 2022).
head and neck squamous cell carcinoma (3 papers, 2023 to 2026). A squamous cell carcinoma that arises from any of the following anatomic sites: lip and oral cavity, nasal cavity, paranasal sinuses, pharynx, larynx, and salivary glands. "While Sideroflexin 3 (SFXN3) consistently displays elevated expression in head and neck squamous cell carcinoma (HNSCC), its specific pathobiological functions and prognostic value remain insufficiently characterized." (PMID 42232609, 2026). "SFXN3 was enriched in neurons 18, which regulated synaptic morphology 19 and the neurodegeneration pathway 20, and SFXN3 overexpression was correlated with immunosuppressive microenvironment in head and neck squamous cell carcinoma and provided prognostic information." (PMID 37786439, 2023).
oral squamous cell carcinoma (3 papers, 2022 to 2024). "Serum anti-SFXN3 levels in oral squamous cell carcinoma were slightly correlated with primary tumor size, and changes in serum anti-SFXN3 levels after treatment were correlated with clinical tumor load." (PMID 38877336, 2024). "In oral squamous cell carcinoma, SFXN3 is not only expressed in cancer cells but also expressed in components of the tumor microenvironment, such as the stromal fibroblasts and the endothelial cells of the small arteries in the cancer nest." (PMID 36159813, 2022). "Serum SFXN3 autoantibody is a novel tumor marker for oral squamous cell carcinoma." (PMID 36618700, 2022).
Alzheimer disease (2 papers, 2022 to 2025). A progressive, neurodegenerative disease characterized by loss of function and death of nerve cells in several areas of the brain leading to loss of cognitive function such as memory and language. "Using high‐resolution proteomics on Sfxn3‐KO mice synapses, we then demonstrate that SFXN3 influences proteins and pathways associated with neurodegeneration and cell death (including CSPα and Caspase‐3), as well as neurological conditions (including Parkinson's disease and Alzheimer’s disease)." (PMID 35092170, 2022). "SFXN1 and SFXN3 are downregulated in both Alzheimer’s disease and PD, both conditions marked by mitochondrial dysfunction." (PMID 40894005, 2025).
Parkinson disease (2 papers, 2021 to 2022). A progressive degenerative disorder of the central nervous system characterized by loss of dopamine producing neurons in the substantia nigra and the presence of Lewy bodies in the substantia nigra and locus coeruleus. "Overexpression of SFXN3 orthologues in Drosophila models of Parkinson's disease significantly reduced dopaminergic neuron loss." (PMID 35092170, 2022).
retinal degeneration (2 papers, 2021 to 2024). Degeneration of the retina. "Accordingly, in mice, Sfxn3 mutations lead to retinal degeneration." (PMID 33494450, 2021). "Retinal thickness even decreased with age in favor of a retinal degeneration due to the lack of functional Sfxn3." (PMID 33494450, 2021).
breast carcinoma (1 paper, 2025). "SFXN3 and ANXA6 had also been reported to be over-expressed in breast cancer." (PMID 39844043, 2025).
tumor (8 papers, 2013 to 2026). "Taken together, a high SFXN3 expression was associated with significantly higher proportions of tumor-infiltrating macrophages." (PMID 36159813, 2022). "Taken together, silencing SFXN3 cause an inhibition of tumor growth." (PMID 38877336, 2024). "Notably, SFXN3 expression was found to be positively associated with enriched tumor-infiltrating macrophages, other immune suppressive cells, and immune checkpoint expression and resistance to paclitaxel." (PMID 36159813, 2022). "The data demonstrated that a high expression of SFXN3 in HNSC associated with tumor progression and poor prognosis might partly be related to enriched tumor-infiltrating macrophages." (PMID 36159813, 2022). "We also explored the potential effect of SFXN3 in affecting the immune cells in the tumor micro-environment via CIBERSORT and ssGSEA." (PMID 38877336, 2024). "During one-carbon metabolism, SFXN3 is a crucial mitochondrial serine transporter that is involved in tumor cell growth." (PMID 37361050, 2023). "The outcomes indicated that there were LTF expression variations in subgroups of tumor stage and N and T stages, SFXN3 in subgroups of tumor stage and M, N, T stage, and TFR2 in subgroups of M, T stage and tumor stage." (PMID 37361050, 2023). "Our study suggested that SFXN3 expression correlated significantly and positively with biomarkers of the main immune-suppressive cells including MDSCs, TAMs, and Tregs, in the tumor microenvironment." (PMID 36159813, 2022). "Next, we explored the relationship between SFXN3 expression and biomarkers of the main immune-suppressive cells including MDSCs, TAMs, and Tregs in the tumor microenvironment." (PMID 36159813, 2022). "Our findings confirmed that SFXN3 promotes tumor hypermethylation in multiple cancers." (PMID 37491851, 2023). "This indicates that SFXN3 plays an important role in regulating tumor genomic hypermethylation." (PMID 37491851, 2023). "Previous studies revealed its effect on mitochondrial serine transport and one-carbon metabolism, which indicated that SFXN3 might be regulating hypermethylation in various tumor genomes." (PMID 37491851, 2023). "Correlation analysis and comparative analysis between groups based on SFXN3 expression indicated that SFXN3 might function as a paclitaxel and docetaxel resistance predictor and is related to enriched tumor‐infiltrating macrophages, immune-suppressive cells, and immune checkpoint expression." (PMID 36159813, 2022). "This may be one of the reasons why SFXN3 is related to the tumor microenvironment." (PMID 36159813, 2022). "PUF60 contributes to apoptosis and transcriptional regulation, SFXN3 is a mitochondrial serine transporter, SERPINB1 regulates the innate immune response, SERPINB5 is a tumor suppressor, and STXBP2 regulates exocytosis." (PMID 36400567, 2023). "The levels of tumor‐infiltrating B cells, CD8+ T cells, dendritic cells, gamma delta T cells, macrophages, NK cells, and plasma cells correlated significantly with SFXN3 expression (all p < 0.05)." (PMID 36159813, 2022). "The function of FBN3, PCNXL3, SFXN3, SRGAP1, VN1R5 and WDR70 have been only marginally evaluated, and their role in the molecular signaling of tumor cells remains largely understudied." (PMID 23577124, 2013). "Moreover, although SFXN3 was reported to be expressed in the stromal fibroblasts around cancer nests, the correlation of SFXN3 with drug resistance and tumor immune infiltration in HNSC has not been determined." (PMID 36159813, 2022). "Finally, we discovered that the 12 IMRGs expression had significant differences, among which SFXN3, TFR2, TMPRSS6, HMOX1, and LCN2 expressions were elevated in the cancer group, and SCARA5, LTF, STEAP2, SLC39A14, CP, ALAS2, and TF were low expressed in the tumor group." (PMID 37361050, 2023).
cancer (6 papers, 2021 to 2026). A tumor composed of atypical neoplastic, often pleomorphic cells that invade other tissues. "The level and prognostic value of SFXN3 were assessed in pan-cancer, especially AML, based on the data obtained from the TCGA database." (PMID 38877336, 2024). "Further, survival curves were plotted using GEPIA to investigate the prognostic value of SFXN3 in pan-cancer (9497 samples)." (PMID 38877336, 2024). "In this research, we firstly analyzed the level and prognostic value of SFXN3 in pan-cancer, especially in AML, based on the data downloaded from TCGA database." (PMID 38877336, 2024). "To explore the possible roles of SFXN3 in pan-cancer, we first analyzed its expression in 22 common cancer types." (PMID 36159813, 2022). "In this study, we performed expression and survival analysis for SFXN3 in pan-cancer using data from The Cancer Genome Atlas (TCGA) and Genotype-Tissue Expression (GTEx) and found that SFXN3 served as a potential oncogene in HNSC." (PMID 36159813, 2022). "To investigate the potential values of SFXN3 expression to predict drug resistance in cancer, we acquired NCI-60 compound activity and corresponding NCI-60 cell line RNA-seq/composite expression from the CellMiner database." (PMID 36159813, 2022). "The level of SFXN3 in 31 types of pan-cancer was identified by GEPIA." (PMID 38877336, 2024). "SFXN3 is a novel and seldom evaluated serine transporter in cancer cell development." (PMID 37491851, 2023). "In this study, we analyzed the expression and prognostic value of SFXN3 in pan-cancer." (PMID 36159813, 2022). "SFXN3, one of the main mitochondrial serine transporters during one-carbon metabolism, might play a crucial role in the development of cancer." (PMID 36159813, 2022). "Taken together, these data demonstrated that SFXN3 was upregulated in CHOL, HNSC, and KIRC, indicating that SFXN3 might act as a crucial regulator in the carcinogenesis of these three cancer types." (PMID 36159813, 2022). "Next, the UALACAN and GEPIA databases were used to validate the expression of SFXN3 in pan-cancer." (PMID 36159813, 2022). "Serine transport may support cancer cell proliferation through the synthesis of nucleotides and one-carbon metabolism, hence SFXN3 may be critical for cancer growth." (PMID 34350187, 2021). "Furthermore, Cox survival analysis was performed on SFXN3 expression in pan-cancer." (PMID 36159813, 2022). "However, few studies have focused on the role of SFXN3 in cancer." (PMID 36159813, 2022). "Sideroflexin 3 (SFXN3) is an important mitochondrial serine transporter during one-carbon metabolism, which is involved in the proliferation of cancer cells." (PMID 36159813, 2022). "SFXN1 as well as SFXN2 and SFXN3 are regulated by the Myc transcription factor and may be involved in cancer cell growth in not yet investigated ways." (PMID 34350187, 2021).
neurodegenerative disease (4 papers, 2022 to 2024). A disorder of the central nervous system characterized by gradual and progressive loss of neural tissue and neurologic function. "We demonstrate that SFXN3 regulates levels of proteins known to be associated with neurodegeneration and cell death pathways (including CSPα and Caspase‐3), as well as constituents of pathways directly associated with several neurodegenerative diseases." (PMID 35092170, 2022). "While SFXN2 has not been previously linked to ALS and is not reported in DisGeNET or ALSoD, its paralog, SFXN3 gene, another member of the SFXN protein family, has been associated with neurodegenerative diseases." (PMID 38672428, 2024). "Currently, SFXN3 has been shown to be involved in various neurodegenerative diseases, such as Parkinson’s disease and Alzheimer’s disease, through synaptic structures." (PMID 38877336, 2024). "Sideroflexin3 (SFXN3) has been shown to be involved in various neurodegenerative diseases." (PMID 38877336, 2024). "Since the steady-state levels of SFXN1 may be decreased in neurodegenerative diseases and its closest homologue SFXN3 may regulate synaptic morphology, we focused on candidate proteins that had been linked to neurological or neurodegenerative disorders." (PMID 36138777, 2022). "Interestingly, previous studies have identified a putative link between SFXN3 and neurodegenerative diseases, as SFXN3 mRNA and protein levels were found to be dysregulated in animal models and patients with PD." (PMID 35092170, 2022).
head and neck tumor (1 paper, 2022). "In our study, we found that SFXN3 expression correlated with paclitaxel resistance by the analysis with data from head and neck tumor cell lines, and there was also a trend toward correlation with docetaxel resistance." (PMID 36159813, 2022).
SFXN3 also shares sentences with these, for which no sentence is quoted: head and neck cancer (2 papers); cholangiocarcinoma (1); lung squamous cell carcinoma (1); prostate adenocarcinoma (1); sarcoma (1).